CDK4 (cyclin dependent kinase 4)
Diseases named in the same sentence as CDK4 in open-access papers (continued):
Sharing a sentence is not in itself a finding about the gene and the disease.
tumor (continued). "As virtually all human tumor cells carry aberrations throughout the cyclin–CDK4/6–RB–p16 axis to support their hyperproliferative state, selective CDK4/6 inhibitors (CDK4/6i) have been developed in recent years." (PMID 34985783, 2022). "Cell cycle-related genes, including CCND1, CDK4, CDKN2A, and RB1, were frequently mutated in MSCs, PCs, and tumor cells." (PMID 35087207, 2022). "It is therefore possible that intermittent CDK4/6i scheduling would potentially have beneficial impacts at both an immune and tumor-intrinsic level." (PMID 35444175, 2022). "Testing for gene mutations responsible for resistance to endocrine or CDK4/6 (cyclin-dependent kinase 4/6) inhibitor therapy either from tumour tissue or free circulating tumour DNA isolated from plasma are another group of multigene tests." (PMID 35845921, 2022). "On the other hand, other studies have highlighted the correlation of the expression of some miRNAs with increased resistance to CDK4/6 inhibitors in different tumor types." (PMID 36498861, 2022). "In particular, CDK4/6 inhibition after chemotherapy or radiotherapy can also enhance tumor suppression in some settings." (PMID 35327487, 2022). "This article aimed to explain the effect of CDK4/6 inhibitors on tumor cells and their efficacy in combination with other drugs." (PMID 35530846, 2022). "One potential mechanism of synergy is that both inhibition of the mitogenic signaling pathway that regulates D-type cyclins, and blocking of CDK4/6 activities, are necessary for a synergized therapy to prevent tumor cell proliferation." (PMID 36185294, 2022). "In summary, the work presented here links CDK4/6 inhibitors with genotoxic stress, which now provides a rationale to better understand how these drugs selectively target tumour cells." (PMID 35037284, 2022). "In this study, we aimed to identify biomarkers of primary and acquired resistance to CDK4/6i in a panel of 37 patient-derived tumor models, using genetic, transcriptomic and proteomic approaches." (PMID 36071033, 2022). "Firstly, this combination (i.e. CDK4/6i plus BRAFi and/or MEKi) potently suppresses tumor proliferation by maintaining RB in an activated, hypophosphorylated state." (PMID 35444175, 2022). "Inhibitors of CDK4/6 can arrest tumor cell development, inhibit the over-proliferation of tumor cells, and prevent abnormal tumor cell replication." (PMID 36744210, 2022). "Especially for LUSC, a comprehensive study of 178 LUSC specimens revealed that significant alteration in CDKN2A and RB1 gene was identified in 72% of LUSC cases, and CDK4/6 gene was frequently amplified in CDKN2A intact tumor." (PMID 36005200, 2022). "In a KRAS (G12C)-mutated and CDKN2A-deficient xenograft model, the combination of MRTX849 and the CDK4/6 inhibitor palbociclib resulted in a significant reduction in tumor volume, showing considerable synergistic effect." (PMID 35922812, 2022). "Collectively, our data provide a strong rationale for clinical testing of dual targeting of FGFR and CCND1/CDK4 in NSCLC patients with FGF3/4/19/CCND1-amplification tumor resistant to gefitinib." (PMID 35814257, 2022). "We show mechanistically that CDK4/6i stabilize primed (pT172) CDK4-cyclin D complex and selectively displace p21 in responsive tumor cells." (PMID 36446794, 2022). "By suppressing the expression of p21 and CDK4 mRNA at the same time, miRNA-503-3p mimic has been shown to function as a tumor growth inhibitor and apoptosis mediator." (PMID 36303933, 2022). "Since CDK4/6 (a p16 target) requires Rb for its kinase activity, p16 acts as a tumor suppressor when functional Rb is present." (PMID 36358806, 2022). "Our results further show that targeting the p16-CDK4/6 interaction sensitizes p16-overexpressing tumor cells to CDK4/6i." (PMID 36071033, 2022).
tumor (continued). "The study furtherly examined that Palbociclib, as the selective CDK4/6 inhibitor, combined with Cetuximab decreased the tumor burden in PDX model." (PMID 36712687, 2022). "Recent studies have also shown that combination treatment of CDK4/6 inhibitors with ICBs exhibits a synergistic effect on tumor control, suggesting that combining these therapies is a remarkable strategy for expanding ICB utility." (PMID 35625867, 2022). "Since deletion of cyclin-dependent kinase inhibitor 2A (CDKN2A), which is a tumor-suppressor gene and a negative regulator of CDK4/6, was found in this Ewing sarcoma patient's tumor, the efficacy of palbociclib was tested on the PDOX model of this tumor." (PMID 36003796, 2022). "Preclinically, we showed that ABZ had a synergistic tumor-eliminating effect with the CDK4/6 inhibitor palbociclib in the treatment of nude mouse models." (PMID 35383224, 2022). "Consistent with the tumor-intrinsic cytostatic effects of CDK4/6i, these inhibitors also dampen proliferation of CTLs via the activation of RB in these cells." (PMID 35444175, 2022). "RB1 is a tumor suppressor that is inactivated by phosphorylation by a complex of CDK4 and CDK6 with cyclin D." (PMID 36003783, 2022). "To obtain a CDK4/6 inhibitor-resistant tumor, we treated the mice with 75 mg/kg/day palbociclib until the tumor regrew under the treatment." (PMID 35664774, 2022). "CDK4/6 inhibitors selectively inhibit CDK4/6, effectively preventing tumor cells from progressing from G1 phase to S phase, restoring cell cycle control, and blocking tumor cell proliferation." (PMID 35783158, 2022). "Tumor burden in mice treated daily with Erk1/2i + CDK4/6i for 4 weeks was significantly (P = 0.0004) reduced compared with animals treated with either the inhibitor alone or DMSO control." (PMID 35082402, 2022). "The inhibition of CDK4/6 blocks the CDK/Rb signaling pathway, causing cell-cycle arrest and thereby inhibiting tumor growth and inducing tumor cell apoptosis." (PMID 36291780, 2022). "To date, most of the studies have been done investigating the effects of miR-34 in NSCLC treatment due to its activity as a master tumor suppressor by silencing its multiple targets (e.g. CDK4, CDK6) involved in cell cycle regulation." (PMID 36303933, 2022). "Currently, biomarkers for selecting patients for CDK4/6i treatment are focussed on tumor-intrinsic factors, such as RB status." (PMID 35444175, 2022). "Restoring p16INK4A expression in DFBM-Ni17 removes the need for CDK4/6 inhibitor to induce tumor response, so that tumors responded to tucatinib alone in the presence of p16INK4A expression." (PMID 35304445, 2022). "It is notable that the combination of CDK4/6 inhibitor and endocrine therapy has led to a greater decrease in the frequency of Ki-67 positive tumor cells in HR-positive, and HER2-negative breast cancer." (PMID 36396665, 2022). "One of these mechanisms is the crosstalk between ER and HER2 signaling, especially the CDK4/6-Cyclin D-Rb signaling axis that is commonly active and has received attention for its potential role in regulating tumor progression." (PMID 35742993, 2022). "Studies have shown that CDK4 is highly expressed in this tumor type and correlates with poor survival and gene signatures that are associated with metastasis." (PMID 36051751, 2022). "In the present study, we investigated the 18F-FES-PET imaging characteristics and tumour responses of patients with MBC who received a CDK4/6 inhibitor combined with endocrine therapy." (PMID 36028895, 2022). "In order to detect the expression of CDK4/6 protein in tumor tissue of nude mice, we processed tumor tissues from xenograft tumor models and detected the expression of CDK4/6 protein in tumors from different groups using immunohistochemistry." (PMID 35479314, 2022).
tumor (continued). "The synergy of this combination has been largely attributed to tumor-intrinsic immunomodulatory activity of CDK4/6 inhibitors; for example through altering MHC I and PD-L1 expression and increasing tumor cell production of T cell chemoattractants." (PMID 35444175, 2022). "Recent functional studies suggest RPL22 acts as a haploinsufficient tumor suppressor involved in inducing senescence through CDK4 inhibition." (PMID 35012638, 2022). "Preclinical models have shown that CDK4/6 inhibitor produce modifications in the tumoral microenvironment and tumor-secreted cytokines resulting in increased T-cell activity and in reducing regulatory T cells activity." (PMID 35053435, 2022). "PD-0332991 is a highly specific inhibitor of cyclin-dependent kinase 4/6 that highly specifically induces G1 phase arrest and thereby inhibits tumor growth." (PMID 36561336, 2022). "In this regard, recent mouse tumor studies have shown that such therapy can augment CDK4/6-induced tumor control." (PMID 35562811, 2022). "Subsequent studies are needed to confirm these results and to determine if other tumor types responsive to CDK4/6 inhibitors also demonstrate similar modulation of [18F]FLT uptake." (PMID 35982453, 2022). "The RB1 mutations were identified at 5, 8, and 13 months after initiation of CDK4/6i in each patient from circulating tumor DNA (ctDNA) analyzed by commercially available NGS-based assay." (PMID 35804935, 2022). "Contrarily, in differentiated cancer cells, FMD stimulates starvation escape pathways, including mTOR, PI3K/AKT, and CDK4/6, thus providing therapeutic targets that can lead to tumour regression with low toxicity." (PMID 36077812, 2022). "Our results extend this observation and show that Pal and two other CDK4/6 inhibitors can also suppress growth of EBV-infected tumor cells as well as KSHV-infected HUVEC cells." (PMID 35562811, 2022). "Inhibitors of cyclin‐dependent kinases 4/6 (CDK4/6i) have recently proven to restrain tumor growth by activating a senescence‐like program in cancer cells." (PMID 34985783, 2022). "In tumor cells, CDK4/6i enhances antigen presentation on major histocompatibility complex (MHC) class I molecules in an RB-dependent manner." (PMID 35248122, 2022). "Previous studies have highlighted that tumor sensitivity to CDK4/6 inhibition require a physiologically functional G1-S restriction point, as well as the absence of mechanisms that activate the cyclin E/CDK2 complex." (PMID 36071033, 2022). "Some investigations of tumor specimens resistant to CDK4/6 inhibitors revealed various possible resistance pathways, including upstream changes in AKT1, KRAS, HRAS, NRAS, FGFR2, and ERBB2." (PMID 35530846, 2022). "Aberrant accumulated β-catenin would translocate to the nucleus and induce the transcription of many oncogenes such as Cyclin-D1-binding protein 1(Cyclin D1) and Cyclin-dependent kinase 4(CDK4), thus promoting tumor progression 23-24." (PMID 36263164, 2022). "Small molecule-inhibitors of cyclin-dependent kinases 4 and 6 (CDK4/6) were initially developed as a therapeutic to block proliferation of tumor cells, specifically targeting tumor types with two key features." (PMID 35444175, 2022). "The promises and dangers surrounding the combined use of CDK4/6 inhibitors and cytotoxic chemotherapeutics are discussed at length in this review, which contains details of the different tumour types that have been shown to benefit from this approach." (PMID 35037284, 2022). "On the other hand, we found that resistance to CDK4/6 inhibitors can be framed at different levels, such as the cell cycle, DNA damage, repair machinery, signaling pathways, and the tumor microenvironment." (PMID 36498861, 2022). "The next goal of precision medicine in pediatric and AYA cancer patients is to understand in detail the tumor adaptive response and develop combination therapies that can mitigate inhibitor resistance, such as that discussed on CDK4/6 inhibition." (PMID 35892870, 2022).
tumor (continued). "CDK4/6 inhibitors (CDK4/6i) were developed as a cancer therapeutic on the basis of their tumor-intrinsic cytostatic potential, but have since demonstrated profound activity as immunomodulatory agents." (PMID 35444175, 2022). "Taken together, our results suggest that although elevated CDK4 levels constitute a tumour progression factor, they also sensitize tumour cells to paclitaxel in a specific manner." (PMID 36477027, 2022). "By contrast, when both CDK6 and CDK4 are coexpressed in a tumor at comparable levels, CDK6 drives Rb/E2F output." (PMID 36051751, 2022). "CDK4/6 inhibitors have been approved only in few clinical indications, although, considering the activity profile CDK4/6 inhibitors, they should work in many histologic tumor types." (PMID 35814409, 2022). "IHC staining revealed that the E2A/c‐Myc and cyclin A2/CDK4 genes in the sh‐E2A tumour group were significantly downregulated, whereas the level of differentiation‐related protein CD11b was upregulated." (PMID 35001521, 2022). "Other data sets exploring acquired resistance are derived from cohorts of tumor biopsies studied at the time of progression on CDK4/6i, sometimes with an accompanying analysis of pre-treatment tissue." (PMID 35248122, 2022). "As CDK4 and CDK6 are crucial factors in tumor cell overproliferation, CDK4/6 inhibition is a potential therapeutic mechanism in these cancers." (PMID 36033522, 2022). "FCN-437c is a novel, selective, potent, and orally active CDK4/6 inhibitor with demonstrated antiproliferative activity in pRb-positive tumor cells derived from a variety of solid tumors." (PMID 36291780, 2022). "For example, mutations of CDK4 and CDK6, which have been found in melanoma and other tumor types, can disrupt the regular progression of the cell cycle." (PMID 35053461, 2022). "These two patients’ tumor samples were RB-proficient, providing rationale for treatment with a CDK4/6 inhibitor." (PMID 35892870, 2022). "Given the recently discovered and profound effects of CDK4/6i on anti-tumor immunity, as clinical trials progress in this area it is important to reflect on the potential caveats of a continuous CDK4/6i schedule." (PMID 35444175, 2022). "Due to the unsatisfactory results of single agents for NSCLC, the combination of CDK4/6i and other conventional therapy is being tested in clinical trials to enhance anti-tumor efficacy." (PMID 35686110, 2022). "There is also a wealth of preclinical evidence that CDK4/6 inhibitors display broad activity against a wide range of other tumour types (for reviews see)." (PMID 35037284, 2022). "Various cyclin‐dependent kinase 4/6 (CDK4/6) inhibitors have demonstrated promising anti‐tumor effects." (PMID 33939324, 2022). "In preclinical pancreatic cancer models, CDK4/6 inhibitors can influence tumor growth and combine to sustain antitumor effects following chemotherapy." (PMID 35273962, 2022). "We aimed to test the anti-tumor effect of ribociclib (a CDK4/6i) combined with pemetrexed on LUAD and the potential mechanisms." (PMID 35686110, 2022). "In contrast, the overexpression of NDUFA4 significantly promoted tumor growth and expression of Cyclin D1 and CDK4 in tumor xenograft." (PMID 35977935, 2022). "We demonstrated that sequential abemaciclib treatment following eribulin-enhanced anti-tumor activity in vitro and in vivo on the CDK4/6 inhibitor-resistant cells by more effectively inhibiting the G2/M cell cycle phase." (PMID 35008374, 2022). "Treatment of tumor bearing mice with CDK4/6 inhibitors has a priming effect on CD8+ T cells, leading to a memory phenotype that has a distinct gene signature and is RB-dependent." (PMID 36051751, 2022). "CDK4/6 enzymes are key promoters of tumour growth in HR + breast cancer and cooperate with oestrogen receptor (ER) pathway activation." (PMID 36028895, 2022).
tumor (continued). "Deeper insight into the mechanisms by which CDK4/6 inhibition (CDK4/6i) modifies tumor biology will be crucial if the full clinical potential of CDK4/6 inhibitors is to be realized." (PMID 35248122, 2022). "RB1, as a tumor suppressor, canonically regulates cell cycle progression and represents a downstream target for CDK4/6 or CDK2 inhibitors that are in clinical use." (PMID 36082941, 2022). "Studies have shown that the marine alkaloids rhopaladins A–D can inhibit the activity of cyclin-dependent kinase 4 and C-erbβ-2 kinase and promote the apoptosis of tumor cells." (PMID 35665067, 2022). "Collectively, these data strongly support the idea that CDK4/6 inhibitors induce tumour immune modulation." (PMID 36135204, 2022). "CDK4/6i‐treated cancer cells not only stop dividing but also activate a potent tumor immunosurveillance." (PMID 34985783, 2022). "Abemaciclib, an inhibitor of CDK4/6 showed anti-tumor effect in HNC patient-derived xenograft harboring CCND1 amplification and/or CDKN2A mutation." (PMID 35372020, 2022). "The expression levels of proteins associated with the cell cycle (CDK4, CDK6 and cyclin D1), proliferation (Ki67 and PCNA) and the pathway (GSK-3β, p-GSK-3β, β-catenin) in tumor tissue samples were determined using western blotting." (PMID 34719320, 2022). "We then detected the protein levels of SH3TC2 and two cell-cycle regulators, CDK4 and Cyclin D1, in the tumor tissues from nude mice by Western blot and found that knockdown of SH3TC2 caused a decrease in CDK4 and Cyclin D1." (PMID 36568637, 2022). "The immunogenicity of CDK4/6i opens up the possibility of combining these inhibitors with immunotherapy to potentiate anti-tumor activity." (PMID 35513054, 2022). "DNA methyltransferase is an E2F target protein that promotes cytotoxic T-cell-mediated tumor inhibition when CDK4/6Is inhibit its activity." (PMID 36358806, 2022). "An immunohistochemical evaluation of the tumors 53 days after inoculation revealed significant suppression of cyclin D1 and cyclin-dependent kinase 4 (CDK4) protein expression, and induced G1 cell cycle arrest and tumor growth inhibition." (PMID 36296903, 2022). "In the study, treatment first with paclitaxel followed by CDK4/6i produced better tumor suppressing activity than when CDK4/6i was administrated first." (PMID 36185294, 2022). "The tumor microenvironment plays an important role in the efficacy of CDK4/6 inhibitors, which have been proven to promote changes in the tumor status through the activation of antitumor immunity." (PMID 36498861, 2022). "As CDK4/6 inhibitors had potent efficacy and tolerable adverse effects, they were used to treat various neoplasms." (PMID 36005200, 2022). "The efficacy of CDK4/6i is incremented by the combination with drugs that prevent the estrogen-dependent stimulation of tumor cells." (PMID 35330128, 2022). "While a number of studies have been focused on CDK4/6 inhibitors to mediate tumor cell cycle arrest, CDK2 can also be a promising target to overcome drug resistance to CDK4/6 inhibitors." (PMID 36305769, 2022). "Recent evidence has brought to light diversified mechanisms of tumor suppression of CDK4/6 SMIs apart from cell cycle arrest." (PMID 35327487, 2022). "The signaling cascade activates Smad1/5, which augments DEC2/SHARP1 levels as well as p27, but inhibits cyclin-dependent kinase 4 (CDK4), bringing the tumor cells into a quiescent state." (PMID 35565234, 2022). "As the first CDK4/6 inhibitor, palbociclib effectively inhibits tumor proliferation by blocking the cell cycle to the G1 phase." (PMID 36091173, 2022). "Tumor cells are positive for CDK4 (left) and MDM2 (right encircled shows nuclear positivity for MDM2)." (PMID 36093467, 2022).